STAT3 (signal transducer and activator of transcription 3)
Diseases named in the same sentence as STAT3 in open-access papers (continued):
Sharing a sentence is not in itself a finding about the gene and the disease.
lung carcinoma (continued). "In an attempt to extend our observations to other cancer types, we analyzed the correlation of TLR4 expression and STAT3 phosphorylation in human liver cancer, lung cancer and stomach cancer tissues using tissue microarray assays." (PMID 32312954, 2020). "Nicotine-induced chemoresistance is mediated by activation of STAT3 in bladder cancer cells 8, 13, in head and neck cancer cells 5, breast cancer cells 6, nasopharyngeal carcinoma 14 and lung cancer cells." (PMID 31956373, 2020). "In lung cancer cells, STAT3 is activated by tyrosine kinases such as epidermal growth factor (EGF) receptor, JAK2, Src, and IL-6R3,5,9,10." (PMID 31900385, 2020). "CHK9 displayed good antitumor activity in lung cancer model with depletion of activated STAT3 and other oncogenic proteins in tumor tissues." (PMID 32967366, 2020). "In osteoblasts, it has been shown that down‐regulation of STAT‐1 or STAT‐3 reduces the expression of CCL‐234 and in a lung cancer cell line, STAT‐1 was linked to IL‐8 expression, whereas TNF‐α synthesis is regulated via NFκB signalling." (PMID 32374474, 2020). "Brevilin A suppresses the phosphorylation of STAT3 at tyrosine 70 to restrict the growth of lung cancer cells." (PMID 32545648, 2020). "Although several heterocyclic systems have been reported to inhibit STAT3 signaling, to best of our knowledge, this is the first report on the STAT3 inhibitory efficacy of oxadiazole-indazole conjugates in lung cancer model." (PMID 32967366, 2020). "Metformin overcomes IL-6-induced EGFR-TKI resistance in TKI-sensitive lung cancer cells through the inhibition of STAT3 and AKT phosphorylation and the enhancement of AMPK activation." (PMID 32041944, 2020). "This study shows that FZKA decoction enhances the effect of Gefitinib-induced lung cancer cells in a mitochondrial pathway through STAT3 and Bcl-2 family." (PMID 32489321, 2020). "To further demonstrate the relationship between p65, IL6, and STAT3 signaling, we overexpressed p65 in lung cancer cells." (PMID 32963220, 2020). "Consistent with that, STAT3 protein expression was undetected in renal cancer and lung cancer, while the expression in normal tissues was medium." (PMID 32486001, 2020). "CHK9 displayed a significant reduction in the number of tumor nodules in the in vivo lung cancer model with suppression of STAT3 activation in tumor tissues." (PMID 32967366, 2020). "Accumulating evidence has demonstrated that activation of STAT3 in both tumor cells and TAMs leads to tumorigenesis and tumor progression in several types of cancers, such as glioblastoma, lung cancer, ovarian cancer, and liver cancer." (PMID 32283687, 2020). "More recently, it has shown that exosome-mediated transfer of certain miRNAs, such as miR-193a-3p, miR-210-3p and miR-5100, can promote metastasis of lung cancer by enhancing STAT3 activity, although the molecular mechanisms await further investigation." (PMID 32972405, 2020). "Activation of PAF/platelet-activating factor receptor (PAFR) promotes lung cancer progression via the activation of Src/STAT3 or JAK2/STAT3." (PMID 31952344, 2020). "Lastly, we demonstrate that targeting STAT3 in EIF3F-overexpressing human lung cancer cells inhibits cell invasion." (PMID 31527668, 2020). "Here, we found that A009 extracts were able to decrease the phosphorylation levels of STAT3 in lung cancer cells, as a potential biochemical mechanisms of cancer prevention." (PMID 32224910, 2020). "Knocking down FAS activates NFkB signaling and subsequent IL6 secretion, resulting in phosphorylation of signal transducer and activator of transcription 3 (STAT3) to promote lung cancer cell growth." (PMID 32963220, 2020). "Together, these results suggested that the FAS downregulation promotes lung cancer cell growth by activating the STAT3 signaling pathway." (PMID 32963220, 2020).
lung carcinoma (continued). "Through ROS-mediated endoplasmic reticulum stress and STAT3 pathways to induce apoptosis in human lung cancer cells, L48H37 also repressed uPA via the JAK/STAT signaling to suppress the migration of human osteosarcoma U2OS cells in the present study." (PMID 33374783, 2020). "We used a combination of imaging, cell biological assays, and mouse xenografts to investigate the role of STAT3 in lung cancer development." (PMID 32087696, 2020). "The M2 macrophages secrete IL-10 in the extracellular media which binds to the IL-10RA, causing the activation of JAK1, STAT1, STAT3, STAT6, NF-κB, and Notch in lung cancer cells." (PMID 32477352, 2020). "Exosomes derived from hypoxic BMSCs were demonstrated to transfer miR‐193a‐3p, miR‐210‐3p and miR‐5100 to lung cancer cells, thus activating STAT3 signalling‐induced EMT and promoting metastasis." (PMID 32391938, 2020). "Because a previous report indicated that MEK inhibition activated STAT3 signaling in KRAS-mutant lung cancer cells, we examined the activation of STAT3 signaling." (PMID 31124056, 2020). "Radiation induces the activation of STAT3 and increases the levels of Bcl-2/Bcl-xL in human lung cancer cells." (PMID 32872659, 2020). "For instance, the circ-HIPK3 transcript acts as a microRNA-124 (miR-124) sponge and regulates the expression of miR-124 mRNA targets, including SphK1, CDK4, and STAT3, in lung cancer cells." (PMID 32692763, 2020). "Overall, CHK9 inhibits the growth of lung cancer cells and tumors by interfering with the STAT3 signaling pathway." (PMID 32967366, 2020). "Impact of PSD-A over TPA and IL-6 induced STAT3 activation has been disclosed previously in lung cancer." (PMID 33013353, 2020). "In essence, research on STAT3/COX-2 has been regarded as an effective method for treating lung cancer." (PMID 33299414, 2020). "Mechanistically, downregulation of LOC389641 was found to decrease EGFR, MET and STAT3 proteins expression in lung cancer cells." (PMID 33318313, 2020). "Both NF‐κB and STAT3 pathways regulate IL‐6 production, which plays an important role in the development and prognosis of lung cancer." (PMID 32020709, 2020). "In fact, transduction of the STAT3 signaling pathway appears to significantly alter the biology of lung cancer cells." (PMID 33299414, 2020). "In previous studies, PSD-A has been found to inhibit STAT3 activation in prostate cancer and A549 lung cancer cells." (PMID 33013353, 2020). "DDIAS expression strongly correlates with STAT3 phosphorylation in human lung cancer cell lines and tissues." (PMID 31900385, 2020). "Our study revealed for the first time that FAS knockdown facilitates STAT3 activation in lung cancer cells." (PMID 32963220, 2020). "Overactivation of EGFR is commonly observed in lung cancers, which lead to the deregulated activation of STAT3 and thereby contribute to the tumor progression." (PMID 32967366, 2020). "In contrast, some studies also report STAT3 being a tumor suppressor in a variety of solid malignancies, including lung cancer." (PMID 32365499, 2020). "STAT3 signaling within tumor and immune cells shapes the TME; the vast majority of lung cancer studies report that STAT3 drives tumor-promoting inflammation while impairing anti-tumor immunity." (PMID 32365499, 2020). "Constitutive STAT3 activation has been observed in several lung cancer cells and tissues, and the restriction of STAT3 activation in a tumor can suppress the expression of pro-proliferative, angiogenetic, and anti-apoptotic genes." (PMID 32150979, 2020). "And the present study demonstrates that Mcl-1 is transcriptional regulated by STAT3 pathway induced by nicotine in human lung cancer cells." (PMID 31956373, 2020). "Thirteen new oxadiazole–indazole hybrids were synthesized and we evaluated their anticancer and STAT3-inhibitory potential in lung cancer cells in vitro and in vivo." (PMID 32967366, 2020).
lung carcinoma (continued). "In order to verify the role (s) of STAT3 and COX-2 towards the antiproliferative activity of BEL in lung cancer cells, Western blot analyses were performed to examine STAT3/p-STAT3 and COX-2 levels in A549 cells after 3 days of BEL treatment." (PMID 33299414, 2020). "IFN-γ secreted by TAMs can induce the expression of PD-L1 in lung cancer cells through JAK/STAT3 and PI3K/AKT signaling pathways, thereby promoting tumor progression." (PMID 33224886, 2020). "Research has uncovered a role for CCL5 in KRAS-induced lung cancer, where it is involved in a cytokine circuit along with IL-6 and STAT3 driving tumorigenesis." (PMID 33116132, 2020). "In conclusion, our study demonstrates a novel anti‐tumour effect of dioscin by inhibiting macrophage M2 polarization via JNK and STAT3 pathways in lung cancer." (PMID 32618105, 2020). "DDIAS knockdown caused growth inhibition of lung cancer cells through STAT3 inactivation by PTPRM, suggesting DDIAS as a potential therapeutic target in aberrant STAT3-activated lung cancer." (PMID 31900385, 2020). "A recent study shows that acetylated STAT3 is able to shuttle between cytosolic and mitochondria of lung cancer cells." (PMID 33382817, 2020). "To investigate the effects of the monobodies on endogenous STAT3 signaling, we inducibly expressed monobodies in A549 lung cancer cells." (PMID 32807795, 2020). "Based on the previous reports, the effect of CHK9 on STAT3 activation in lung cancer cells was investigated and CHK9 was found to decrease the phosphorylation of STAT3Y705 in the tested cell lines." (PMID 32967366, 2020). "Our results indicate that high expression of microRNA-608 inhibits the proliferation, migration, and invasion of lung cancer cells by targeting BRD4 via the JAK2/STAT3 pathway." (PMID 31621555, 2020). "The MAPK, STAT3 and NF-κB signalling pathways were inhibited by HHDMNQ, and they were closely associated with the suppression of proliferation and induction of A549 lung cancer cell apoptosis." (PMID 32849902, 2020). "In summary, our findings reveal a reciprocal regulation of miR‐206 and IL‐6/STAT3 pathway that mediates IL‐6‐induced gefitinib resistance in EGFR‐mutant lung cancer cells." (PMID 31507089, 2019). "Considering the complexity of transcription and signaling networks, further investigation is needed to confirm the function of STAT3 in the regulation of PD-L1 in resistant lung cancer." (PMID 30842489, 2019). "To further investigate the clinical relevance of our findings, we performed immunohistochemical staining to assess the CDK1, GP130, and p-STAT3 expression in lung cancer tissues and adjacent normal lung tissues." (PMID 30931929, 2019). "In this study, we demonstrated that autophagy enhanced VEGFA expression of lung cancer cells via activation of JAK2/STAT3 signaling pathway both in vitro and in vivo." (PMID 30755242, 2019). "Overexpression of STAT3 in Non-Small Cell Lung Cancer (NSCLC) patients is a strong predictor of poor prognosis, cationic solid lipid nanoparticles (cSLN) were used to deliver RNAi-mediating plasmid DNA targeting STAT3 in cisplatin resistant lung cancer cells." (PMID 30847297, 2019). "The present study revealed the role of the transcriptional repression of miRNAs, such as miR-145-5p, by the STAT3-G9a axis in EGFR-positive lung cancers, which exacerbated HER3 expression and led to EGFR-TKI resistance." (PMID 31619200, 2019). "First, we validated that the knockdown of STAT3 reduced the viability of lung cancer cells significantly, which is consistent with the results of our previous study that demonstrated that STAT3 facilitated the survival of colorectal cancer stem-like cells." (PMID 31619200, 2019). "In the present study, we investigated the effect of STX-0119, which inhibiting STAT3 dimerization, on the cell growth in lung cancer cell lines in vitro and in vivo." (PMID 32257917, 2019).
lung carcinoma (continued). "Single-drug BBR has an obvious inhibitory effect on lung cancer cells; BBR can inhibit doxorubicin (DOX)-mediated STAT3 activation and sensitize lung cancer cells to the cytotoxic effects of DOX treatment." (PMID 31208348, 2019). "Then, we found that lung cancer cells induced ADSCs to secrete high levels of IL-6 family cytokines and activate the STAT3 signalling pathway." (PMID 31196220, 2019). "MiR-410 down-regulation increases the expression of SOCS3 leading to the decreased level of STAT3 protein and minimized progression of lung cancer cells." (PMID 31569687, 2019). "Altogether, the present results suggest a potential preventive and treatment strategy for lung cancer via suppression of GP130/STAT3 signaling via CDK1 inhibition or iron deprivation." (PMID 30931929, 2019). "In lung cancer mouse models, blocking or deleting IL-6 reveals a delay in tumor progression and metastasis through deactivation of the IL-6/STAT3 pathway and cell proliferation regulator cyclin D1, as well as through enhancement of tumor cell apoptosis." (PMID 32039025, 2019). "STAT1 and STAT3 were also tested because STAT1 was reported to be a transcription factor for CFH in response to the stimulation of IFN-γ, and STAT3 is an oncogene that is also reported to be increased in lung cancers." (PMID 30987235, 2019). "In fact, IL-6/STAT3 signaling has been shown to suppress lung cancer initiation while promoting cancerous cell proliferation, migration, and disease progression by positively modulating the induction of cyclin D1." (PMID 31547048, 2019). "A high dose of quercetin (66 μM) was found to reduce p-STAT3 levels in lung cancer cells after a long incubation period (12–24 h) by an indirect effect on NF-κB activation and IL-6 production." (PMID 31491838, 2019). "The anti-cancer effects of ACEE in lung cancer cells are mediated at least in part by down-regulation of the JAK2/STAT3 signaling pathway." (PMID 30914735, 2019). "In this study we found that STAT3 signaling activation regulated PD-L1 expression in cisplatin-resistant lung cancer cells." (PMID 30961670, 2019). "Here, we investigated the role of miR‐206 in regulating IL‐6/STAT3 pathway and gefitinib resistance in lung cancer." (PMID 31507089, 2019). "Overall, these findings strongly indicated that KLF3 acts as a crucial suppressor of lung cancer by regulating metastasis via STAT3 expression." (PMID 31486564, 2019). "Despite these findings, the reason for the abnormal activation of STAT3, especially in lung cancer, has yet to be determined." (PMID 31486564, 2019). "Next, we investigated the role of JAK2/STAT3/VEGFA pathway in the anti-angiogenic potential of anlotinib in lung cancer cell." (PMID 30755242, 2019). "KLF3 expression was negatively correlated with STAT3 and vimentin expression in the clinical lung cancer specimens." (PMID 31486564, 2019). "BBR sensitizes lung cancer cells to Doxorubicin by promoting STAT3 degradation, inhibiting doxorubicin mediated STAT3 activation." (PMID 30837865, 2019). "Altogether, the present results suggest that CDK1 inhibition and iron deprivation are potential strategies to target GP130/STAT3 signaling to suppress lung cancer." (PMID 30931929, 2019). "In H157 lung cancer cells, sema3F inhibited multiple signaling pathways including Protein kinase B (AKT)/Signal transducer and activator of transcription 3 (STAT3) signaling resulting in the loss of activated αvβ3-integrin." (PMID 30696103, 2019). "BBI608 and YM155 demonstrated similar effects, reducing the viability of lung cancer A549 cells and inhibiting STAT3-mediated G9a and HER3 expression." (PMID 31619200, 2019). "To exclude the possibility that oxidative stress activates STAT3 signaling and promotes sphere formation directly in our study, we treated lung cancer cells with the antioxidant butylated hydroxyanisole (BHA, 100 μM)." (PMID 30931929, 2019).
lung carcinoma (continued). "Overall, these results indicated that the KLF3/STAT3 signaling axis plays a crucial role in lung cancer metastasis." (PMID 31486564, 2019). "Altogether, these results show T21 as a potent anticancer compound that effectively decreases survivin levels through STAT3 inhibition in lung cancer, appearing as a promising therapeutic drug for cancer treatment." (PMID 31412593, 2019). "Because HER3 facilitates EGFR-TKI resistance, our results indicate that the STAT3 blockade is a promising strategy that can be employed to eradicate EGFR-TKI-resistant lung cancers, including KRAS-mutant A549 and T790 M-mutant H1975 cells." (PMID 31619200, 2019). "Mechanistically, WA inhibited oncogenic signaling in lung cancer, namely, the mTOR/STAT3 pathway, indicating that WA exerted an anti–lung cancer effect." (PMID 31319622, 2019). "More importantly, bioinformatics analysis and in vitro experiments indicated that the role of KLF3 in lung cancer metastasis is dependent on the STAT3 signaling pathway." (PMID 31486564, 2019). "In this study, we investigated a novel small-molecule inhibitor, named STX-0119, to target STAT3 in lung cancer cells." (PMID 32257917, 2019). "Evidence on the effect of Stat3 upon GJIC stems mainly from Src-transformed, rodent cells as well as from human lung carcinoma lines and expression of a mutationally activated form of Stat3." (PMID 30717267, 2019). "The role that STAT3 plays in lung cancer is controversial due to opposite findings by various researches." (PMID 32039025, 2019). "The present study is the first to illustrate that LDOC1 functions as a bridge between tobacco smoke exposure and IL-6/JAK2/STAT3 activation in lung cancer." (PMID 30634502, 2019). "STAT3 inhibitor-loaded SLNs significantly sensitized lung cancer cells to cisplatin-mediated apoptosis." (PMID 31569687, 2019). "In particular, the data revealed a novel regulatory mechanism of the IL-6/JAK2/STAT3 loop in the pathogenesis of lung cancer." (PMID 30634502, 2019). "STAT3 is active constitutively in a variety of human cancer cells and tissues, including multiple myeloma and lung cancer." (PMID 31058868, 2019). "Past works from our team demonstrated that garcinol inhibited STAT3 activation and suppressed the lung cancer stem cell population." (PMID 31783691, 2019). "Consistently, RelA or STAT3 co-deletion or knockdown decreased growth gene expression and lung cancer cell growth." (PMID 31757943, 2019). "Our findings suggested that the KLF3/STAT3 signaling pathway is a potential therapeutic target for patients with lung cancer." (PMID 31486564, 2019). "To further evaluate the role of the KLF3/STAT3 signaling pathway in lung cancer metastasis in vivo, we performed a rescue experiment in a mouse model." (PMID 31486564, 2019). "We showed that forced miR‐206 expression restored gefitinib sensitivity in IL6‐induced gefitinib‐resistant EGFR‐mutant lung cancer cells by inhibiting IL6/JAK1/STAT3 pathway." (PMID 31507089, 2019). "The results showed that the phosphorylation levels of Jak3 and Stat3 were induced by IFN-γ in lung cancer cells." (PMID 32038231, 2019). "CDK1, GP130, and p-STAT3 were upregulated in lung cancer tissues compared with adjacent normal lung tissues." (PMID 30931929, 2019). "STX-0119 inhibited persistent STAT3 phosphorylation and induced apoptosis in lung cancer cell lines." (PMID 32257917, 2019). "Another study demonstrated that the lncRNA MALAT1 contributes to cisplatin resistance and modulates P-gp expression in lung cancer via the STAT3 pathway." (PMID 31920517, 2019). "STX-0119 inhibited activated STAT3 and the expression of STAT3-regulated oncoproteins such as c-Myc, cyclin D1, and survivin in lung cancer cells." (PMID 32257917, 2019). "In the present study, we demonstrate that exposure to MH leads to a decline in p-STAT3 levels in human A549 lung cancer cells with very similar kinetics to that observed in MDA-MB-231 cells." (PMID 31491838, 2019).